CEP350 (centrosomal protein 350)
Description:
Plays an essential role in centriole growth by stabilizing a procentriolar seed composed of at least, SASS6 and CPAP. Required for anchoring microtubules to the centrosomes and for the integrity of the microtubule network. Recruits PPARA to discrete subcellular compartments and thereby modulates PPARA activity. Required for ciliation.
Synonyms: CAP350; KIAA0480; GM133
Tractability: PROTAC: ubiquitination databases record sites on it; its protein half-life has been measured.
Gene: Protein-coding gene on chromosome 1 (179,954,674 to 180,114,880, forward strand). Ensembl gene ENSG00000135837.
Subcellular location: Cytoplasm, cytoskeleton, microtubule organizing center, centrosome; Cytoplasm, cytoskeleton, spindle; Nucleus; Cytoplasm, cytoskeleton, microtubule organizing center, centrosome, centriole; Cytoplasm, cytoskeleton, cilium basal body
Subcellular location (Human Protein Atlas): Centrosome; Nucleoplasm; Basal body; End piece
Gene Ontology:
Molecular function: protein binding; microtubule binding
Biological process: protein localization to centrosome; microtubule anchoring
Cellular component: centriole; centrosome; ciliary basal body; membrane; nucleoplasm; nucleus; spindle
Genetic constraint (gnomAD): Loss-of-function variants: 83 observed, 247.65 expected, observed/expected ratio (o/e) 0.34, 90% interval 0.28 to 0.4. The upper end of that interval is the gene's LOEUF score, 0.4, which puts it in group 1 of 6, group 1 being the genes least tolerant of losing a copy. Missense variants: 3,001 observed, 3,178.1 expected, observed/expected ratio (o/e) 0.94, 90% interval 0.92 to 0.97. Synonymous variants: 1,053 observed, 1,112.7 expected, observed/expected ratio (o/e) 0.95, 90% interval 0.9 to 1.
Homologues: Orthologues: chimpanzee CEP350 (99% identical), macaque CEP350 (97% identical), dog CEP350 (88% identical), pig CEP350 (85% identical), rabbit CEP350 (83% identical), mouse Cep350 (80% identical), rat Cep350 (79% identical), zebrafish cep350 (42% identical), tropical clawed frog cep350 (37% identical).
Diseases named in the same sentence as CEP350 in open-access papers:
CEP350 is named in the same sentence as 11 diseases in open-access papers, as found by Europe PMC text mining. Sharing a sentence is not in itself a finding about the gene and the disease. The quoted sentences say what the papers report.
ciliopathies (1 paper, 2017). "Together, these data demonstrate a role for the CEP19, FOP and CEP350 module in ciliogenesis and the possible effect of disrupting their functions in ciliopathies." (PMID 28659385, 2017). "Interestingly, a morbid-obesity-associated R82* truncated mutant of CEP19 cannot ciliate nor interact with FOP and CEP350, indicative of a putative role for CEP19 in ciliopathies." (PMID 28659385, 2017).
cancer (3 papers, 2013 to 2021). A tumor composed of atypical neoplastic, often pleomorphic cells that invade other tissues. "Indeed, although not represented on either of the curated CGC or TSGdb lists, several genes (e.g., Cep350, Ncoa2, and Usp9x) have all been observed in other SB tumor screens and experimentally validated to be TSGs within mouse models and/or human cancer cells." (PMID 33435458, 2021).
CEP350 also shares sentences with these, for which no sentence is quoted: asthenozoospermia (1 paper); chronic pancreatitis (1); cyst (1); infection (1); Leber congenital amaurosis (1); Obesity (1); pancreatic cancer (1); tumor (1); virus infection (1).